LINC02560 (long independently transcribed non-coding RNA 2560)
Synonyms: CTD-2619J13.13
Gene: Long non-coding RNA gene on chromosome 19 (58,400,221 to 58,400,679, forward strand). Ensembl gene ENSG00000268307.
Diseases named in the same sentence as LINC02560 in open-access papers:
LINC02560 is named in the same sentence as 6 diseases in open-access papers, as found by Europe PMC text mining. Sharing a sentence is not in itself a finding about the gene and the disease. The quoted sentences say what the papers report.
basal cell carcinoma (1 paper, 2021). A carcinoma involving the basal cells. "Furthermore, negative regulation of epithelial to mesenchymal transition, the PPAR signaling pathway, WNT signaling pathway, basal cell carcinoma, MAPK signaling pathway and regulation of actin cytoskeleton were significantly enriched in high expression of LINC02560." (PMID 35003370, 2021).
colorectal cancer (1 paper, 2021). A primary or metastatic malignant neoplasm that affects the colon or rectum. "However, the expression of LINC02560 in colorectal cancer (CRC) has not been reported, and its correlation with tumor development and function is still unclear." (PMID 35003370, 2021).
hepatocellular carcinoma (1 paper, 2025). A malignant tumor that arises from hepatocytes. "LINC02560 promotes the proliferation, invasion, and immune escape of hepatocellular carcinoma (HCC) by directly binding to GLI2 protein, regulating its epigenetic modifications, and interacting with other signaling pathways." (PMID 40681919, 2025). "In hepatocellular carcinoma, there is a complex interaction network among multiple genes, which jointly regulate cell growth, differentiation and apoptosis.LINC02560 is a key node in these interactive networks." (PMID 40681919, 2025). "For example, LINC02560 has a more specific expression pattern and a more complex regulatory mechanism in hepatocellular carcinoma." (PMID 40681919, 2025). "These regulatory mechanisms act together on the promoter and transcripts of LINC02560, thus affecting its expression level in hepatocellular carcinoma." (PMID 40681919, 2025). "Through further study on the function and mechanism of LINC02560 in hepatocellular carcinoma, We can provide new ideas and methods for the diagnosis and treatment of hepatocellular carcinoma." (PMID 40681919, 2025). "These regulatory factors act on the promoter, transcript and translation process of LINC02560.Thereby affecting the expression level of the protein in the hepatocellular carcinoma." (PMID 40681919, 2025). "Through in vitro cell experiments and animal model experiments, They found that overexpression of LINC02560 significantly promoted the proliferation and invasion of hepatocellular carcinoma cells." (PMID 40681919, 2025). "In hepatocellular carcinoma, LINC02560 regulates GLI2 through a complex mechanism." (PMID 40681919, 2025). "In addition to its cancer-promoting effect, LINC02560 was found to have the function of regulating cancer cell metabolism in hepatocellular carcinoma." (PMID 40681919, 2025). "In addition, LINC02560 is also involved in the metabolic regulation, immune escape and drug resistance of hepatocellular carcinoma." (PMID 40681919, 2025). "LINC02560 is also involved in immune escape in hepatocellular carcinoma." (PMID 40681919, 2025). "Secondly, LINC02560 can also bind to specific miRNAs as ceRNA (competitive endogenous RNA).So as to relieve the inhibitory effect of miRNA on other target genes, and then regulate the progress of hepatocellular carcinoma." (PMID 40681919, 2025). "In conclusion, LINC02560 regulates GLI2 through complex mechanisms and plays an important role in the occurrence and development of hepatocellular carcinoma." (PMID 40681919, 2025). "In particular, the interaction between LINC02560 and GLI2 provides a new perspective for understanding the morbidity mechanism of hepatocellular carcinoma.LINC02560 has been shown to regulate GLI2 through a variety of mechanisms." (PMID 40681919, 2025). "The interaction between LINC02560 and GLI2 further enriches our understanding of the mechanism of morbidity in hepatocellular carcinoma." (PMID 40681919, 2025). "In addition, LINC02560 regulation of GLI2 also affects the therapeutic effect and prognosis of hepatocellular carcinoma." (PMID 40681919, 2025). "The aim of this study was to investigate the expression and function of LINC02560 in hepatocellular carcinoma, and to elucidate the mechanism of its regulation of GLI2.Through this study, we expect to provide new ideas and methods for the treatment of hepatocellular carcinoma." (PMID 40681919, 2025).
tongue squamous cell carcinoma (1 paper, 2021). A squamous cell carcinoma that arises from the tongue. "For example, LINC02560 has been demonstrated to be a potential biomarker and significantly associated with the overall survival of tongue squamous cell carcinoma of patients." (PMID 34136488, 2021).
cancer (4 papers, 2019 to 2025). A tumor composed of atypical neoplastic, often pleomorphic cells that invade other tissues. "Further investigation of LINC02560’s biological mechanisms may yield novel insights into early diagnosis and personalized cancer treatment." (PMID 40427523, 2025).
tumor (4 papers, 2021 to 2025). "This indicates that LINC02560 is involved in tumor progression and evolution, promoting tumor proliferation and lymph node metastasis." (PMID 35003370, 2021). "The relative expression of LINC02560 in tumor cell lines was significantly higher than that in normal colon epithelial cells." (PMID 35003370, 2021). "In addition, the results of the high expression of LINC02560 in CRC tumor tissues have been verified in our own 10 fresh CRC tumors and para-cancerous samples." (PMID 35003370, 2021). "Furthermore, the starBase online database indicated that miR-505-5p was expressed at higher levels in normal tissues than in tumor tissues, whereas LINC02560 exhibited elevated expression in PTC tissues, while the expression levels of miR-505-5p and LINC02560 showed an inverse correlation." (PMID 40427523, 2025). "Similarly, when expanding our investigation to in vivo models, we found that mice injected with cells that overexpress LINC02560 exhibited a notable rise in tumor volume and weight, along with higher KI67 protein levels in the removed tumor tissues." (PMID 40427523, 2025). "Nevertheless, the expression of LINC02560 in tumor tissues has not been reported, and the correlation between its expression and tumor development and its function is still unclear." (PMID 35003370, 2021). "In addition, the expression of AC091729.3, AL133371.2, PCED1B‐AS1, LINC02560, and AC242842.1 was significantly different at different tumor stages in the training and whole cohort." (PMID 34077998, 2021).